CCND1 (cyclin D1)
Diseases named in the same sentence as CCND1 in open-access papers (continued):
Sharing a sentence is not in itself a finding about the gene and the disease.
tumor (continued). "To verify the inhibition of tumor growth in vivo was caused by MCM7 knockdown, we further detected the expression of MCM7 and cyclin D1 in those xenograft tumors." (PMID 28182015, 2017). "In this case, Roniciclib treatment down-regulates c-Myc in tumour cells and relieves the suppression of CCND1 by c-Myc." (PMID 28246384, 2017). "The growth-promoting functions and deregulated expression of cyclin D1 increases tumor proliferation in several human cancers." (PMID 29242565, 2017). "Nonetheless, consistent with our in vitro proliferation studies, IHC analysis revealed reduced c-Myc and Cyclin D1 expression in Kaiso-depleted MDA-231 tumors compared to control MDA-231 tumor tissues." (PMID 28333150, 2017). "Over-expression of WDR11 resulted in the down-regulation of WNT signaling pathway and regulators of G1 progression including Myc and D-type cyclins, Ccnd1,2 and 3 consistent with the delay in tumor development and increased survival." (PMID 29029386, 2017). "The expression of STAT3 downstream genes (cyclin D1 and Mcl-1) was also detected by real-time quantitative PCR, and samples from Atn-treated mice showed downregulated cyclin D1 and Mcl-1 mRNA expression levels compared with tumor tissues from vehicle mice." (PMID 27861147, 2017). "The ability of cyclin D1 to drive the cell cycle forward can be blocked by cyclin D1-dependent kinase (CDK) inhibitors, such as p27 and p21, and can explain why co-expression of cyclin D1 and p21 contributed to the role of cyclin D1 for tumor proliferation." (PMID 28938543, 2017). "Wnt5a/ROR2 signaling is associated with suppression of β-catenin/TCF-dependent transcriptional activity and down-regulated the expression of cyclin D1 in erythroleukemia cells, suggesting its anti-tumor role on cell proliferation." (PMID 29213214, 2017). "Taken together, our findings suggest a model in which miR-363-3p regulates both the mTOR/Cyclin D1 pathway and the Erk-cyclin D1 pathway to inhibit tumor cell growth." (PMID 28423618, 2017). "We found a significant positive correlation between MCM7 and cyclin D1 expression in HCC tumor tissues that confirmed the involvement of MCM7–cyclin D1 pathway in HCC." (PMID 28182015, 2017). "Tumor tissue samples were analyzed the expression of IL-20 and cyclin D1 by using immunohistochemistry staining and quantitative real-time polymerase chain reaction (qRT-PCR) analysis." (PMID 29242565, 2017). "This inhibition of Wnt signaling within tumor cells led to reduced levels of β-catenin, which caused a reduction in the expression of VEGF, matrix metalloproteinase (MMP)-7 and Cyclin D1, as well as triggering apoptosis of the tumor cells." (PMID 28974047, 2017). "PKM2-dependent β-catenin transactivation and CCND1 expression are instrumental in EGFR-promoted tumor cell proliferation and brain tumor development." (PMID 29299177, 2017). "Box plots showing the differential expression of LAST and CCND1 between normal (n = 10) and tumor (n = 165) samples." (PMID 29199958, 2017). "Cyclin D1 is one of the most crucial cell cycle regulatory proteins, serving pivotal roles in the pathogenesis of several human tumor types including CRC." (PMID 28427191, 2017). "The cyclin D1 predictive value of tumor response value in pretreatment tumor rectal biopsies is little studied." (PMID 28938543, 2017). "In conclusion, our study demonstrates that miR-503 has a tumor suppressor role in ESCC cell lines and tumor samples by negatively regulating the expression of its direct target, CCND1, in ESCC." (PMID 28602785, 2017). "In this study, we addressed this question by measuring the expression of CXCR4, CXCL12, and Cyclin D1 proteins in tumor samples from Chinese patients with sporadic MPNST." (PMID 29020982, 2017). "For instance, amplifications in 8q21 have been associated with high tumour grade, high levels of Ki67 and other proliferation markers, including MYC, MDM2 and CCND1." (PMID 28351365, 2017).
tumor (continued). "The genes in the leading edge of the GSEA included Myc, Ccnd1 and Ccnd2, consistent with the delay in tumor development in mice harboring G3 MB overexpressing WDR11." (PMID 29029386, 2017). "We found that IL-20 was associated with cyclin D1 mRNA expression in patients with HCC and three human HCC cell lines, which indicates that IL-20 was involved in tumor growth in HCC." (PMID 29242565, 2017). "Overexpression of cyclin D1 contributes to malignant properties of tumor cells by increasing VEGF production and decreasing Fas expression." (PMID 28764703, 2017). "Recurrently identified miR-193b targets relevant to its tumor/metastasis suppressive roles in these contexts have included cyclin D1, and urokinase-type plasminogen activator." (PMID 28542597, 2017). "One recent study found that CPD exerted anti-tumor effects in sarcoma S180 tumor-bearing mice by down-regulating the expression Wnt/β-catenin and Cyclin D1." (PMID 29228681, 2017). "With regards to the hepatic expression of cyclin D1, Bcl-3Hep mice exhibited increased levels of Ccnd1 in liver and tumor tissue compared to the wild type, which were unaffected by DEN/PB-treatment." (PMID 28915576, 2017). "c-Myc plays a essential role in this Roniciclib-impacting ESC-like signature, which is evident by the occupancy of c-Myc at both the CDK2 and CCND1 promoters in tumor." (PMID 28246384, 2017). "CCND1 amplification correlated significantly with higher tumor grade (p = 0.038), high Ki-67 protein expression (p = 0.002), and Luminal B subtype (p = 0.002): 13 of 17 cases (76.5%) with high amplification were the Luminal B subtype." (PMID 29140993, 2017). "MiR-195 exerts its tumor suppressive function by targeting CCND1 and FGF2 and restraining the activity of the Wnt/β-catenin signaling." (PMID 28740507, 2017). "We investigated again the levels of the proliferation marker Ccnd1 in whole tumor lysates by Western blot analysis." (PMID 28112237, 2017). "In this study, we investigated the anti-cancer effect of quercetin on HepG2 tumor-bearing nude mice and its effect on cyclin D1 expression in the tumor tissue." (PMID 28264020, 2017). "Analysis of heterotypic signals induced by stromal cyclin D1 identified activation of heterocellular signaling that promoted tumor inflammation, angiogenesis and stem cell expansion." (PMID 29137220, 2017). "Knockdown of β-TrCP blocks Cyclin D1 turnover induced by berberine; blocking the protein degradation induced by berberine in HepG2 cells increases tumor cell resistance to berberine." (PMID 27854312, 2016). "Reduced expression of active β-catenin and its downstream target genes c-Myc and cyclin D1 was also observed in PCDH17-transfected tumor cells (MB468, MCF7 and MB231) by western blot." (PMID 27351130, 2016). "In conclusion, a high level of cyclin D1 expression, together with poor tumor cell differentiation and advanced AJCC stage, increased risk of postoperative distant metastasis and decreased survival in patients with resectable ESCC." (PMID 27145270, 2016). "In conclusion, our results demonstrated that miR- 146a-5p acted as a tumor suppressor through directly targeting CCND1 and CCND2 in the NSCLC cell lines, H1299 and SPCA-1." (PMID 27494902, 2016). "Next we detected the phosphorylation of ERK1/2 and JNK, Cyclin D1, Bcl-2, Caspase 3 and Bax in tumor tissue." (PMID 26901856, 2016). "Herein silencing cyclin D1 induced in vivo changes in tumor vascularity and structural organization, impairing the amplitude and architecture of the vascular bed." (PMID 26689991, 2016).
tumor (continued). "In conclusion, this work suggested that miR-202 is down-regulated in the progression and development of CC through inhibition of cyclin D1 expression, and miR-202 can be recommended as a effective tumor-suppressing miRNA." (PMID 27732565, 2016). "STAT3 promotes cancer proliferation and/or survival directly by regulating target genes of tumour cells such as survivin, cyclin D1 and Bcl-xL." (PMID 26909593, 2016). "Reconstitution of either cyclin D1 or CDK4 in Tspan5-overexpressing GC cells rescues the inhibitory phenotype produced by Tspan5, suggesting that cyclin D1/CDK4 play a dominant role in mediating the suppression of tumour growth by Tspan5 in GC." (PMID 27223087, 2016). "Our findings establish a new link between cyclin D1 and metabolism in both tumor cells and physiologic hepatocyte proliferation." (PMID 27351284, 2016). "In R3327-5′A rat tumour cells that had Ccnd1 downregulated by RNA interference, activated Rac1 levels depended on Ccnd1 because transfecting these cells with human Ccnd1 restored the wild-type levels of activated Rac1." (PMID 27181366, 2016). "Three hours after seeding on fibronectin, mouse-embryonic fibroblasts and tumor-endometrial cells showed Ccnd1 in the membrane of spreading cells." (PMID 27105504, 2016). "We examined miR-374a levels by in situ hybridization and its correlation with CCND1 expression in CRC tumor tissues." (PMID 27191497, 2016). "It is known that cyclin D1 is a protein required for progression through the G1 phase of the cell cycle, and the retinoblastoma protein (Rb), which is a tumor suppressor, is inactivated while Rb is phosphorylated to p-Rb (Ser807/811)." (PMID 27783047, 2016). "CCND1 is a proto-oncogene and a good biomarker for tumor progression, found to be deregulated in several cancers, including RCC." (PMID 27766950, 2016). "In the mice xenografted with tumor cells expressing cyclin D1-shRNA, tumor progressions occurred within 12 and 14 days after the T0 in PC3 and 22Rv1 tumor cells, respectively." (PMID 26689991, 2016). "Patients treated with 5-FU-based chemotherapy carrying the CCND1 rs9344 A/A genotype had significantly decreased time-to-tumor recurrence." (PMID 26884752, 2016). "This is based on data showing ErbB2-driven tumor arrest and senescence in vivo in response to acute cyclin D1 ablation or targeted inhibition of CDK4/6." (PMID 26857361, 2016). "Collectively, these results suggest that Prx I positively affects activation of H-rasG12V-induced pERK and cyclin D1 expression to promote hepatic-tumor growth." (PMID 27517622, 2016). "Our data demonstrates that miR-374a functions as a tumor suppressor by directly reducing CCND1, in contrast with previous reports that miR-374a acts as oncogene by modulating tumor suppressors WIFI, PTEN and WNT5A." (PMID 27191497, 2016). "A high level of cyclin D1 expression, together with poor tumor cell differentiation and advanced tumor stages, increased risk of postoperative metastasis and decreased distant metastasis-free survival in ESCC in both cohorts." (PMID 27145270, 2016). "MiR-214 is a tumor suppressor miRNA that can directly or indirectly targets β-catenin to inhibit cell growth by down-regulating c-Myc, cyclin D1, TCF-1 and LEF1 in HCC." (PMID 27556491, 2016). "Mechanistically, Tspan5 suppresses the tumour growth through regulating the cell cycle transition from G1-S phase by increasing the expression of p27 and p15 and decreasing the expression of cyclin D1, CDK4, pRB and E2F1." (PMID 27223087, 2016). "This was true for Ccnd1−/− fibroblasts, R3327-5′A tumour cells wherein Ccnd1 was knocked down with RNA interference, or Ccnd1+/+ fibroblasts treated with 2 μM Palbociclib, a specific inhibitor of Ccnd1·Cdk4." (PMID 27181366, 2016). "The in vivo effect of the PIN1 inhibitor on cyclin D1 repression was further confirmed by the intra-tumor injection of Juglone into C666-1 xenografts in nude mice models." (PMID 27258148, 2016).
tumor (continued). "We confirmed that exposure of tumor cells to thrombin significantly increased cell proliferation and this was coupled with downregulation of p27 and concomitant induction of cyclin D1." (PMID 27600331, 2016). "We also observed decreased STAT3 activation and cyclin D1 expression in tumor biopsies from HepG2-WT-HCMV-injected mice as compared with controls." (PMID 27626063, 2016). "Previous studies mostly focused on single miRNA, such as miR-138, a potential tumor suppressor by targeting CCND1." (PMID 26795575, 2016). "Here, we show that the localization of Ccnd1·Cdk4 in the membrane of fibroblasts and tumour cells has an active role in the induction of cell migration and invasion through the phosphorylation of Pxn." (PMID 27181366, 2016). "Treatment with HuR-FNP reduced HuR protein levels in the tumor cells with concomitant reduction in cyclin-D1 and -E and increased P27 protein expression, an observation that concurred with previous reports." (PMID 27328938, 2016). "Significant associations emerged between EGFR amplification and large tumor size (T4), ER-negative and HER2-positive status, between CCND1 amplification and HER2-positive and MIB1-positive status, and between ESR1 deletion and ER-negative status." (PMID 27765917, 2016). "GSK3β is constitutively active in unstimulated cells and acts as a “tumor suppressor” since maintains in inactivate state different molecules related to cell growth, such as cyclin D1 or c-Myc." (PMID 27634891, 2016). "Cyclin D1 was also reported as the substrate of β-TrCP in tumor cells under glucose starvation or particular anti-tumor agent treatment." (PMID 27854312, 2016). "We found that cyclin D1 expression was dramatically decreased in SGC-7901-shHOXA1 and BGC-823-shHOXA1 cells compared to the levels in the corresponding control cells, which indicates that HOXA1 influences tumor cell proliferation by regulating cyclin D1." (PMID 26791264, 2016). "It is well accepted that Ccnd1 nuclear accumulation is indicative that the tumor has a significant mitotic activity." (PMID 27105504, 2016). "Here, we used patient tumor samples and 4 SyS cell lines to evaluate genetic alterations of CCND1 and the expression patterns of the proteins playing a possible role in deregulation of this axis." (PMID 27334220, 2016). "In this study, we have found an increase of the membranous-cytoplasmic Ccnd1 expression in cells from specific invasion patterns (single cell/small cell clusters, buds, glandular) in which tumor cells are in contact with the adjacent stroma." (PMID 27105504, 2016). "We then reconstituted cyclin D1 in Tspan5-overexpressing tumour cells by transfection with the pENTER-cyclin D1 expression vector." (PMID 27223087, 2016). "In CRC, tumor buds showed lower nuclear Ki-67 levels (i.e., lower proliferation) and higher nuclear p16INK4, cyclin D1, and β-catenin levels, as compared to the main tumor mass." (PMID 27136592, 2016). "FGS enhanced the functions of CDDP in cell apoptosis and in blocking the G1 transition, which was associated with decreased cyclin D1 and increased p21 in LLC and LLC-derived tumor tissue." (PMID 27721894, 2016). "We infected R3327-5′A rat tumor cells that had endogenous Ccnd1 downregulated by RNA interference with lentiviruses containing human HA-Ccnd1, HA-Ccnd1-CAAX or HA-Ccnd1K112E-CAAX or empty vector." (PMID 27105504, 2016). "As ARID2 repression is closely correlated with cell proliferation and invasiveness, the expression of cell growth and aggressiveness markers Ki-67, E2F1, cyclin D1, and cyclin E1 were then evaluated in tumor tissues." (PMID 27351279, 2016). "In this current study, we have shown that Daxx silencing reduces tumor growth by suppressing cyclin D1 expression in OSCC." (PMID 26205068, 2016).
tumor (continued). "The cluster of miR-15a/miR16-1 was reported to target Bcl-2, CCND1 (encoding cyclin D1) and WNT3A, leading to tumor cell growth arrest and apoptosis." (PMID 27151407, 2016). "An enforced expression of Wnt5a led to a degradation of β-catenin and a reduced expression of Cyclin D1 and capacity of colony formation, indicating that Wnt5a acted as a tumor suppressor role in CRC by suppressing the canonical Wnt signaling pathway." (PMID 27895670, 2016). "To link ceased tumor outgrowth to arrested cell cycle progression, we performed immunohistochemistry to examine the intensity of cyclin D1 and p21 staining on collected tumors." (PMID 27901486, 2016). "When characterizing tumor cell proliferation, we found an increased number of Ki67 positive cells, consistent with increased Cyclin D1 mRNA levels in tumor cells of HFD compared to ND mice." (PMID 27049717, 2016). "This in turn results in an increase of cyclin D1 (CCND1) and c-Myc expression, thereby promoting tumor cell growth and brain tumorigenesis." (PMID 27340866, 2016). "In tumor cells, activation of Stat3 involve in regulation of anti-apoptotic genes and cell cycle regulators, such as Bcl-xL, Bcl-2, Cyclin D1 and PCNA." (PMID 27563884, 2016). "Cyclin D1 (Ccnd1) is a proto-oncogen amplified in many different cancers and nuclear accumulation of Ccnd1 is a characteristic of tumor cells." (PMID 27105504, 2016). "In the present study, we demonstrated that cyclin D1 governs the tumor phenotype and participates in determining radioresistance of PCa cells independently by androgen receptor expression." (PMID 26689991, 2016). "Our data demonstrate the importance of Daxx in regulation of cyclin D1 expression and provide the first evidence that Daxx exhibits tumor-promoting activity in OSCC." (PMID 26205068, 2016). "The expression of the cell proliferation markers Ki67 and cyclin D1 in Huh7 tumor tissues was analyzed using immunohistochemical analysis." (PMID 27502492, 2016). "Genetic depletion of β-TrCP attenuates berberine′s inductive action on Cyclin D1 degradation as well as berberine′s anti-tumor effect." (PMID 27854312, 2016). "Of note, the expression of Wnt target genes Axin 2, c-Myc, Cyclin D1 and survivin was significantly reduced in the tumor tissues treated with Bisleuconothine A sulfate, as well as the induction of Ser33/37/41 phosphorylation of β-catenin." (PMID 26862734, 2016). "Although the baseline tumour also had amplified MYC and CCND1, these were distinct events with breakpoints different than those observed in the surgical tumour." (PMID 27502118, 2016). "Our findings in this study indicate berberine′s potential as an anti-tumor agent with clear mechanism in inducing Cyclin D1 degradation." (PMID 27854312, 2016). "Tumor cells harboring Ccnd1-CAAX showed high levels of invasiveness and metastatic potential compared to those containing the wild type allele of Ccnd1." (PMID 27105504, 2016). "In skin tumorigenesis, PS-1 can cause β-catenin /LEF mediated cyclin D1 activation, thus arresting cell entry from G1 into S phase and regulating cell proliferation." (PMID 26872378, 2016). "The age distribution, tumor location, surgical approaches, pathological nodal categories, and cyclin D1 expression were well balanced between the two patient cohorts." (PMID 27145270, 2016).